LDHA (lactate dehydrogenase A)
Diseases named in the same sentence as LDHA in open-access papers (continued):
Sharing a sentence is not in itself a finding about the gene and the disease.
multiple sclerosis (2 papers, 2020 to 2023). A progressive autoimmune disorder affecting the central nervous system resulting in demyelination. "Intravenous treatment of multiple sclerosis patients with the GC methylprednisolone decreased the expression in peripheral T cells of metabolic genes, including LDHA." (PMID 38567068, 2023). "Under conditions such as hypoxia and multiple sclerosis, the expression of LDHA is increased, and inhibition of LDHA suppresses the inflammation reaction." (PMID 32321555, 2020). "LDHA (lactate dehydrogenase) is downstream of HIF-1α and is reported to promote inflammation in multiple sclerosis." (PMID 32321555, 2020).
Nephropathy (2 papers, 2023 to 2025). A nonspecific term referring to disease or damage of the kidneys. "Segmental sclerosis was more prominent in podocyte-specific LDHA-deficient mice with adriamycin-induced nephropathy than in control mice." (PMID 40980659, 2025).
oligodendroglioma (2 papers, 2025). A well-differentiated (WHO grade II), diffusely infiltrating neuroglial tumor, typically located in the cerebral hemispheres. "For example, CpG sites in the lactate dehydrogenase A (LDHA) promoter were identified among the top features relevant for oligodendroglioma, as indicated by positive weights and hypermethylation of the nearby CpG island, while CpG sites in the gene body were not differentially methylated." (PMID 40481322, 2025).
oncocytomas (2 papers, 2019). "Proteomic analysis showed that 14-3-3η was overexpressed in oncocytomas, and inhibited lactate dehydrogenase A (LDHA) through direct interaction." (PMID 30945144, 2019).
oral cancer (2 papers, 2015 to 2019). "LDHA, another important glycolytic gene, is up-regulated in many cancers including oral cancer, and regulates cancer cell proliferation, metastasis, angiogenesis and immune escape." (PMID 31638999, 2019). "As expected, CDDP re-sensitized the Tax R cells through the inhibition of LDHA, and this effect was reversed following overexpression of LDHA in the parental oral cancer cells." (PMID 25789051, 2015). "CDDP treatments downregulated LDHA expression, and lower levels of LDHA were detected in the CDDP-resistant oral cancer cells compared with the CDDP-sensitive cells." (PMID 25789051, 2015). "The present study next checked the LDHA expression levels in response to Taxol treatment in the oral cancer cells." (PMID 25789051, 2015). "In the present study, it was found that CDDP treatment resulted in decreased LDHA expression levels in the oral cancer cells, while Taxol treatment showed the reverse results, with an increased level of LDHA expression." (PMID 25789051, 2015). "The present study also revealed the synergistic cytotoxicity of CDDP and Taxol for killing oral cancer cells through the inhibition of LDHA." (PMID 25789051, 2015). "The present study results showed that decreased levels of LDHA were responsible for the resistance of oral cancer cells to cisplatin (CDDP)." (PMID 25789051, 2015). "This study highlights LDHA as a novel therapeutic target for overcoming Taxol resistance in oral cancer patients using the combined treatments of Taxol and CDDP." (PMID 25789051, 2015). "The aim of this study was to identify whether LDHA was involved in oral cancer cell resistance to Taxol and whether the downregulation of LDHA, as a result of cisplatin treatment, may overcome Taxol resistance in human oral squamous cells." (PMID 25789051, 2015). "Whether synergistic cytotoxicity of cisplatin and Taxol on Taxol resistant oral cancer cells occurs via the inhibition of LDHA was also explored." (PMID 25789051, 2015). "Treatment with BME on oral cancer cell lines significantly reduced mRNA and protein expression levels of key glycolytic genes SLC2A1 (GLUT-1), PFKP, LDHA, PKM and PDK3." (PMID 31638999, 2019).
ovarian tumor (2 papers, 2018 to 2025). "High LDHA expression in ovarian tumors was strongly associated with poor patient survival, consistent with prior clinical observations." (PMID 41422325, 2025). "Real-time measurements and metabolomic analysis in primary ovarian tumor cells indicated that lactate secretion was markedly higher in LDHA-high samples." (PMID 41422325, 2025).
pancreatitis (2 papers, 2016 to 2024). Inflammation of the pancreas. "The differential expression pattern suggests that PKM2 (or a combination of PKM2 and LDHA) would be a better choice for discriminating cancer from pre-neoplastic lesions compared with LDHA alone, except in pancreatitis where both markers are highly expressed." (PMID 26989901, 2016). "In both cohorts, pancreatitis samples also highly expressed LDHA compared with PKM2 expression." (PMID 26989901, 2016). "Interestingly, our results demonstrate overexpression of LDHA at a very early stage along the carcinogenetic pathway from pancreatitis through cyst/PanIN to cancer with the highest expression in the most aggressive tumours." (PMID 26989901, 2016). "Among them, three genes (HMGB2, LDHA and AKT3) were reported to be closely related to pancreatitis, and no gene was reported to be associated with EBV infection." (PMID 39546499, 2024). "In contrast, LDHA expression was generally high in tumour as well as in preneoplastic tissues and pancreatitis without a specific pattern." (PMID 26989901, 2016).
pharyngeal squamous cell carcinoma (2 papers, 2016 to 2023). A squamous cell carcinoma that arises from the pharynx. "Our data are consistent with studies in cervical and pharyngeal squamous cell carcinomas demonstrating increased LDHA expression in response to hypoxia, likely mediated by hypoxia-inducible factor 1 (HIF-1)." (PMID 37107600, 2023). "When they repeated the experiment in a pharyngeal squamous cell carcinoma cell line, they found that LDHA mRNA expression also gradually increased as oxygen concentrations decreased from 21% to 0.01%; however, changes in pHe had little effect on LDHA mRNA expression." (PMID 26269128, 2016).
renal fibrosis (2 papers, 2024). A final common manifestation of a wide variety of chronic kidney diseases characterized by glomerulosclerosis and tubulointerstitial fibrosis. "In addition to regulating lipid metabolism to alleviate renal fibrosis, it also inhibits glycolysis by reducing the expression of HK2 and lactate dehydrogenase A (LDHA) in NRK-52E cells." (PMID 39465434, 2024).
silicosis (2 papers, 2021 to 2022). Silicosis is a respiratory disease caused by breathing in (inhaling) silica dust. "Our previous studies found that the expression of LDHA, a key enzyme involved in glycolysis, was increased in silica-induced macrophages and silicotic models, and it was closely related to silicosis fibrosis by participating in inflammatory response." (PMID 35328434, 2022). "In this study, we also found high levels of LDHA and lactate in silicotic models, suggesting the potential effect of LDHA on silicosis." (PMID 34576239, 2021). "We also examined the expression of other key enzymes in the glycolytic pathway and found that the protein and mRNA expression levels of HK2, pyruvate kinase M2 (PKM2), and LDHA were also increased in rats with silicosis." (PMID 34576239, 2021). "In previous studies, the levels of LDHA and its metabolic product, lactate, were increased in silica-induced rats and mice, indicating that LDHA might be an effective potential therapeutic target for silicosis." (PMID 35328434, 2022). "Our previous studies showed that the mRNA and protein levels of lactate dehydrogenase A (LDHA) were upregulated in rats that inhaled silica, suggesting a potential role of LDHA in the glycolysis of silicosis." (PMID 34576239, 2021).
small cell lung carcinoma (2 papers, 2014 to 2024). Small cell lung cancer (SCLC) is a highly aggressive malignant neoplasm, accounting for 10-15% of lung cancer cases, characterized byrapid growth, and early metastasis. "MA treatment of small cell lung carcinoma DMS114 cells caused downregulation of glycolytic proteins (ALDOA, GAPDH, ENO1, PyKM2 and LDHA) as well as upregulation of OxPhos proteins (cytochrome b-c1 complex subunit 2 and cytochrome c oxidase subunit 5B)." (PMID 39288141, 2024).
thyroid (2 papers, 2015 to 2025). "In this study we investigated the expression of PKM2, LDHA and FGFR1 in thyroid benign and malignant tissues by employment of qPCR and western blot." (PMID 25880801, 2015).
tuberculosis (2 papers, 2020 to 2023). A chronic, recurrent infection caused by the bacterium Mycobacterium tuberculosis. "Using lung tissue from tuberculosis (TB) patients and myeloid deficient LDHA (LdhaLysM−/−) mice, we demonstrate that glycolysis in myeloid cells is essential for protective immunity in TB." (PMID 37673914, 2023). "Likewise, co-administration of a known small molecule LDHA inhibitor and an anti-tuberculosis drug has improved the tuberculosis therapeutic outcomes in murine models." (PMID 32034005, 2020). "Here, we sought to determine the importance of LDHA for tuberculosis (TB) disease progression and its potential as a target for host-directed therapy." (PMID 32034005, 2020). "To this end, we orally administered FX11, a known small-molecule NADH-competitive LDHA inhibitor, to M. tuberculosis-infected C57BL/6J mice and Nos2−/− mice with hypoxic necrotizing lung TB lesions." (PMID 32034005, 2020).
age-related macular degeneration (1 paper, 2023). Age-related loss of vision in the central portion of the retina (macula), secondary to retinal degeneration. "Glucose shortage is associated with retinal diseases, such as age-related macular degeneration (AMD), and regulating the levels of LDHA may have therapeutic relevance." (PMID 36896135, 2023).
alveolitis (1 paper, 2023). "Further association of LDHA with immune cell function in the human TB lung can be made based on positive LDHA staining within giant cells, lymphoid aggregates, and alveolitis." (PMID 37673914, 2023).
anaplastic cancer (1 paper, 2022). "In fact, after either co-culture with anaplastic cancer cells or treatment with tumor cell-derived conditioned medium, human fibroblasts significantly enhance the expression of both the glucose transporter GLUT-1 and the glycolytic enzyme lactate dehydrogenase A (LDH-A)." (PMID 36077709, 2022).
anemia (1 paper, 2016). A reduction in the number of red blood cells, the amount of hemoglobin, and/or the volume of packed red blood cells. "Since LDHA expression is under the control of HIF1α transcription factor, it could be involved in the response of immature erythroid progenitors to anemia." (PMID 28027290, 2016).
anxiety disorder (1 paper, 2020). A category of psychiatric disorders which are characterized by anxious feelings or fear often accompanied by physical symptoms associated with anxiety. "Furthermore, a single conserved exon 5 haplotype in LDHA is remarkably associated with the risk of panic disorder, which is a type of anxiety disorder." (PMID 32830860, 2020).
Aortic dissection (1 paper, 2025). Aortic dissection refers to a tear in the intimal layer of the aorta causing a separation between the intima and the medial layers of the aorta. "Therefore, the protective effect of the LDHA inhibitor on aortic dissection cannot be solely attributed to reduced lactylation levels." (PMID 40800583, 2025).
brain aneurysm (1 paper, 2025). A congenital or acquired aneurysm within the cranium. "Expanding on this understanding, our study focused on investigating the impact of LDHA modulation on vascular EC (VEC) proliferation and migration in brain aneurysm patients." (PMID 38829380, 2025).
brain cancer (1 paper, 2025). A primary or metastatic malignant neoplasm affecting the brain. "For instance, VEGFA, HK2, and LDHA are linked to the HIF-1 signaling pathway and glycolysis/gluconeogenesis, underscoring their roles in the metabolic adaptations of the metastatic brain cancer cells." (PMID 40038276, 2025).
brainstem gliomas (1 paper, 2025). "Our findings suggest that this advanced metabolic imaging technique may be used for the noninvasive characterization of molecular hypoxia and lactate dehydrogenase-A activity in these pediatric brainstem gliomas." (PMID 41226138, 2025).
chronic hepatitis B (1 paper, 2024). "Consistent with our in vitro findings, in people with chronic hepatitis B there was significantly increased expression of PDK1, PDK2, and PDK3 compared to healthy liver, with a strong trend towards increased expression of LDHA (P =0.057)." (PMID 38655824, 2024).
cyst (1 paper, 2016). A sac-like closed membranous structure that may be empty or contain fluid or amorphous material. "PKM2 expression increased progressively from cyst through PanIN to cancer, whereas LDHA was overexpressed throughout the carcinogenic process." (PMID 26989901, 2016).
cystic fibrosis (1 paper, 2021). Autosomal recessive disorder caused by pathogenic variants in the CFTR gene (cystic fibrosis transmembrane conductance regulator), which encodes a chloride and bicarbonate channel expressed in epithelial cells, and follow the diagnosis criteria. "The levels of LDHA and its metabolic product, lactate, were increased in patients with IPF, bleomycin-induced mice, and radiation-induced mice, TGF-β-induced lung fibroblasts, and cystic fibrosis lung epithelial IB3-1 cells." (PMID 34576239, 2021).
dementia (1 paper, 2023). Loss of intellectual abilities interfering with an individual's social and occupational functions. "LDHA was also found to be upregulated in AD compared to the non-AD dementia groups." (PMID 37461556, 2023).
endothelial dysfunction (1 paper, 2022). In vascular diseases, endothelial dysfunction is a systemic pathological state of the endothelium (the inner lining of blood vessels) and can be broadly defined as an imbalance between vasodilating and vasoconstricting substances produced by (or acting on) the endothelium. "Finally, recovery of miR-30c-5p in NORAD-overexpressing HPMECs effectively overrode the NORAD-promoted glycolysis and impaired endothelial dysfunction under LPS stimulation by targeting LDHA." (PMID 35480402, 2022).
erythroplakia (1 paper, 2023). "Across control, erythroplakia, and cancer, L-lactate dehydrogenase A chain was upregulated whereas aldehyde dehydrogenase 2, peroxiredoxin 1, heat shock 70 kDa protein 1B, and spectrin alpha chain, nonerythrocytic 1 were downregulated." (PMID 36776920, 2023).
esophageal tumor (1 paper, 2022). "To demonstrate the importance of LDH subunit A in esophageal tumor growth, we analyzed the expression level of LDHA genes in esophageal tumor tissue samples and compared it to the level determined for normal control tissues." (PMID 36555705, 2022).
follicular lymphoma (1 paper, 2015). Follicular lymphoma is a form of non-Hodgkin lymphoma characterized by a proliferation of B cells whose nodular structure of follicular architecture is preserved. "The other genes, such as HK2, CENPF, CTPS, LDHA, P2RY5 and DNASE1L3 also can be identified in both transformation follicular lymphoma and ‘indolent’ type FL." (PMID 26416427, 2015).
gestational diabetes mellitus (1 paper, 2016). "MiR-410 represses LDHA expression and promotes embryonic stem cells (hESC) to differentiate into pancreatic endoderm (PE) in gestational diabetes mellitus treatment." (PMID 27458165, 2016).
glucose metabolic disorders (1 paper, 2019). "Our results reveal that LDHA induces glucose metabolic disorders and stabilizes USP28 expression." (PMID 30688660, 2019).
goiter (1 paper, 2015). Enlargement of the thyroid gland usually caused by lack of iodine in the diet, hyperthyroidism, or thyroid nodules. "Analysis of LDHA transcripts by employment of RT-PCR analysis revealed significantly up-regulated expression in UTC as compared to goiter." (PMID 25880801, 2015). "The median expression of total LDHA was 54.9% in goiter, 75% in FA, 81.5% in FTC, 97.4% in PTC and 72.5% in UTC." (PMID 25880801, 2015). "Phospho-LDHA / total LDHA ratio showed significantly increased relative phosphorylation in all cancer subgroups in comparison to goiter." (PMID 25880801, 2015). "Analysis of phosphorylated LDHA revealed higher levels of LDHA in each cancer subgroup (PTC, FTC and UTC) in contrast to goiter." (PMID 25880801, 2015). "UTC and FA demonstrated a noticeable, but not significant increase in total LDHA expression compared to goiter." (PMID 25880801, 2015). "Expression of LDHA in PTC showed an increased tendency as compared to goiter or FA, however, these differences were not significant." (PMID 25880801, 2015). "LDHA was found markedly higher in FTC compared to FA or goiter without a statistical difference observed." (PMID 25880801, 2015). "UTC revealed a noticeable, however not significant up-regulation of LDHA as compared to goiter." (PMID 25880801, 2015).
HIV-1 infection (1 paper, 2023). The type species of lentivirus and the etiologic agent of acquired immunodeficiency syndrome (AIDS). "HIF-1α–activating genes, including HK2, PDK1, and LDHA (which function vitally in the glycolytic pathway), were also up-regulated by HIV-1 infection." (PMID 37798121, 2023).
infectious colitis (1 paper, 2022). A viral or bacterial infectious process affecting the large intestine. "Furthermore, mice lacking the lactate dehydrogenase A subunit in intestinal epithelial cells exhibited lower levels of inflammation in a model of non-infectious colitis." (PMID 36434690, 2022).
injury (1 paper, 2024). Damage inflicted on the body as the direct or indirect result of an external force, with or without disruption of structural continuity. "In the CCl4-induced liver injury mice model, the effect of Sal B and 2-DG on plasma lactate was examined, while the expression of Pan Kla, LDHA, NLRP3, and IL-1β proteins was also detected and quantitatively analyzed by immunohistochemistry." (PMID 38202819, 2024). "According to the results, Sal B targets the LDHA protein to interfere with the production of lactate, following the induction of a low level of histone lactylation in M1 macrophages, and the results were also confirmed in a mouse model of CCl4-induced liver injury." (PMID 38202819, 2024).
insomnia (1 paper, 2020). A sleep disorder characterized by difficulty in falling asleep and/or remaining asleep. "The insomnia-associated gene of LDHA has co-expression links with predicted genes of PGK1 and RARS." (PMID 32830860, 2020). "In conclusion, the current comprehensive study provides multiple lines of evidence for supporting DALRD3, LDHA, HEBP2, TEX264, and FGFR3 as insomnia-associated genes whose abnormal expression level may convey risk to insomnia." (PMID 32830860, 2020). "Furthermore, by conducting a DGE analysis, we found that three genes of DALRD3 (P=5.0 × 10−5), LDHA (P=0.044), and HEBP2 (P=0.032) showed significantly down-regulated expression in insomnia brain samples compared with controls." (PMID 32830860, 2020).
intracerebral hemorrhage (1 paper, 2025). A cerebrovascular disorder characterized by bleeding into one or both cerebral hemispheres including the basal ganglia and the cerebral cortex.
invasive carcinoma (1 paper, 2021). A carcinoma that is not confined to the epithelium, and has spread to the surrounding stroma. "Like SLC2A1, LDHA was found to increase expression during the transition from precancerous lesions to invasive carcinomas, and multiple studies have confirmed that LDHA is closely related to tumor initiation and progression." (PMID 34977159, 2021).
ischemic heart disease (1 paper, 2025). "Future studies should aim to elucidate the specific mechanisms of nuclear LDHA in cardiomyocytes and evaluate whether targeting nuclear LDHA serves as a promising strategy for cardiac repair in ischemic heart disease." (PMID 40710803, 2025).